ENSG00000238142 (novel transcript)
Synonyms: LOC105376805
Gene: Long non-coding RNA gene on chromosome 1 (16,887,535 to 16,896,642, reverse strand). Ensembl gene ENSG00000238142.
Gene Ontology:
Molecular function: triplet codon-amino acid adaptor activity
Biological process: translation